MKI67 (marker of proliferation Ki-67)
Diseases named in the same sentence as MKI67 in open-access papers (continued):
Sharing a sentence is not in itself a finding about the gene and the disease.
triple-negative breast carcinoma (210 papers, 2007 to 2026). An invasive breast carcinoma which is negative for expression of estrogen receptor (ER), progesterone receptor (PR), and human epidermal growth factor receptor 2 (HER2). "Markers for cell proliferation like Top2a, Birc5, and Mki67 are highly expressed, so are markers for metastasis like Msln, Ect2, and Plk1, which are known to be overexpressed in triple-negative breast cancer (TNBC)." (PMID 32793490, 2020). "All patients’ tissue biopsy samples were examined to check the expressions of the estrogen receptor, progesterone receptor, human epidermal growth factor receptor 2 (HER2), and the Ki67 (MKI67) value, and two patients belonged to the triple-negative breast cancer (TNBC) group." (PMID 39330049, 2024).
cervical carcinoma (192 papers, 1992 to 2026). A carcinoma arising from either the exocervical squamous epithelium or the endocervical glandular epithelium. "MKI67, encoding the proliferation marker protein Ki-67, is correlated with the progression of several cancers such as laryngeal squamous cell cancer, gastroenteropancreatic neuroendocrine tumors, and cervical cancer." (PMID 32883335, 2020). "Further analysis of mRNA expression data retrieved from the DepMap platform confirmed our previous observations and showed a positive correlation between the H2Bub1 score and MKi67 or PCNA in cervical cancer (CC) cell lines." (PMID 40597205, 2025). "As an exploration, we also assessed the correlation between TPP1 and MKI67 gene expression using TCGA data from the GEPIA database in cervical cancer." (PMID 38722833, 2024). "On the other hand, TIPE1 expression was elevated, and its expression was positively correlated to MKI67 expression in cervical cancer tissues." (PMID 36118167, 2022). "Of the top 10 ranked upregulated genes, 2 have not been previously reported as associated with cervical cancer (NUSAP1, and CDKN3), while the other 8 have been associated with cervical cancer either scantly (SYCP2, PRC1, CCNB2 and CDC20) or widely (MKI67, CDKN2A, CDC2, and PCNA)." (PMID 23405241, 2013). "Interestingly, we found that mRNA expression of TPP1 was positively correlated with the expression of MKI67, suggesting that TPP1 could be linked to the proliferation and malignancy of cervical cancer." (PMID 38722833, 2024).
adenoma (185 papers, 2003 to 2026). A neoplasm arising from the epithelium. "The expression of MKI67 has been gradually increased from normal tissue, adenomas to adenocarcinomas, in CRC patients." (PMID 31207989, 2019). "MKI67, the most frequently used cell proliferation marker in the clinical setting, was significantly elevated in CRC tissue compared to adenoma tissue (p = 0.008)." (PMID 33668713, 2021). "On the other hand, the expression levels of MKI67 were not statistically different between CRC and adenoma organoids, despite a difference in median value, likely because of the large variance and small sample size of CRC organoids (p = 0.187)." (PMID 33668713, 2021).
glioblastoma (166 papers, 2007 to 2026). The most malignant astrocytic tumor (WHO grade IV). "Furthermore, PROM1, a marker associated with tumor stemness and glioblastoma progression, showed a positive correlation with MKI67 in some tumor models." (PMID 40917877, 2025). "We scrutinized the expression of DIAPH3 at single cell level and detected an overlap with MKI67 expression in glioblastoma proliferating cells, including neural progenitor-like, oligodendrocyte progenitor-like and astrocyte-like states." (PMID 38454929, 2024). "Moreover, in spheroids obtained from glioblastoma 35 and neuroma 46-1, these changes were predominantly unidirectional, and the most pronounced decrease was shown by the Cdkn2a and Mki67 genes involved in the regulation of proliferation and the cell cycle." (PMID 38672482, 2024). "By contrast, in spheroids derived from glioblastoma 14-60-4, the Cdkn2a and Mki67 mRNA levels were unchanged, and the transcription rates for Pik3cg, Pten, and Abcb1b increased dramatically, while Sox2 expression decreased, reaching minimal values recorded in the whole experiment." (PMID 38672482, 2024). "For instance, the MKI67 gene, a well‐established marker of cellular proliferation used widely in cancer grading and prognosis, showed significant correlation with C1GALT1 in nearly all tumor types evaluated, except for glioblastoma." (PMID 40548474, 2025). "Though bioinformatic analyses suggest that TOP2A may be associated with ferroptosis, further studies are needed to figure out the whole gene regulation network that contains MKI67 and TOP2A in glioblastoma ferroptosis." (PMID 37834393, 2023). "Finally, as we previously found that NOTCH1 activation drastically reduced the rate of proliferation of glioblastoma stem cells, we also assessed the effect of NICD on the proliferation of LGG275 cells by measuring the expression of the proliferation marker MKI67 by IF and QPCR." (PMID 33925547, 2021). "However, their overexpression was observed to repress the cell proliferation and migration, and invasion of GBM through downregulating the IGF2BP1 levels, which reduces the level of c-MYC, CD44, MKI67, and PTEN mRNA in GBM cells or blocks G1/S transition in glioblastoma cell." (PMID 29954406, 2018). "It is not clear whether the downregulation of MKI67 and TOP2A are just induced by increased oxidative stress in ferroptotic glioblastoma cells or whether these two genes also take part in the regulation of ferroptosis." (PMID 37834393, 2023).
colon carcinoma (165 papers, 2006 to 2025). "For stage II/III colon cancer with mismatch repair defects and microsatellite instability, MKI67 may be a useful biomarker for diagnosis and prognosis evaluation." (PMID 40594780, 2025). "It has been demonstrated that MKI67 plays an important role in colon cancer." (PMID 30186855, 2018). "In line with this notion, we found that expression of the generic proliferation marker MKI67, WNT- and MYC-target genes, and the KEGG pathway ‘cell-cycle’ are expressed at significantly lower levels in CMS4 than in any of the other subtypes in primary colon cancer." (PMID 36147916, 2022).
colorectal cancer (164 papers, 1999 to 2026). A primary or metastatic malignant neoplasm that affects the colon or rectum. "Two independent colorectal cancer cohorts comprising 1,839 patients were analyzed using multiplex IHC for MKI67 (Ki-67), CD8, and CK." (PMID 41201451, 2026). "MKI67 is a potential diagnostic and prognostic biomarker in microsatellite instability stage II/III high colorectal cancer." (PMID 39830364, 2025). "For instance, the low expression group of Ki67 had a longer OS than the high one in LUADLUSC, while the increased expression of MKI67 had a longer OS in Colorectal carcinoma(COADREAD)." (PMID 40070823, 2025). "Among the prognostic risk factors, SNRPA1 was reported to be highly expressed in colorectal cancer tissues and promoted cancer progression through the regulation of PIK3R1, VEGFC, MKI67, and CDK1." (PMID 36212157, 2022). "Consequently, the MKI67+ TCs subpopulation may contribute to immune signaling and enhance inflammatory responses inside TME of potential colorectal cancer, hence facilitating the identification of novel immunotherapy targets." (PMID 40842994, 2025). "Thus using scRNAseq data, we verified that most of the single cells expressing MKI67 and the cells expressing vimentin do not overlap, which suggests that the high proliferation subgroup and mesenchymal subgroup are distinct subgroups in colorectal cancers." (PMID 34256801, 2021). "MKI67 and PCNA were used as positive markers, and CDKN1A was used as a negative marker for cell proliferation in colorectal cancer." (PMID 34548081, 2021).
gastric cancer (164 papers, 2006 to 2026). A primary or metastatic malignant neoplasm involving the stomach. "TPX2 and MKI67 have been recognized as prominent genes in gastric cancer, with elevated TPX2 expression linked to tumor progression and poor survival outcomes, suggesting its potential role as a biomarker for adverse prognosis or a target for future therapeutic strategies in gastric cancer." (PMID 40445003, 2025). "For instance, MKI67 is a potential indicator to predict the prognosis of patients with stomach cancer and identify high-risk cases, and TYMS may be potential biomarkers for prognosis and chemotherapy guidance for stomach cancer." (PMID 36226184, 2022). "Gastric cancer (GC) threatens human health worldwide and we performed this meta-analysis to evaluate the clinical value of Ki-67/MKI67 in patients with GC." (PMID 31632479, 2019). "Especially, we revealed the potential of Ki-67/MKI67 as a prognostic biomarker in advanced gastric cancer patients." (PMID 31632479, 2019). "We found that an over-expressed Ki-67/MKI67 could differentiate gastric cancer patients from normal subjects." (PMID 31632479, 2019). "We highlighted genes, including TPX2, MKI67, EXO1, and CTHRC1, as potential biomarkers for early diagnosis, prognostic evaluation, and therapeutic targeting in gastric cancer." (PMID 40445003, 2025). "Of the 53 included records, 3 records compared the expression of Ki-67/MKI67 in gastric cancerous and adjacent non-cancerous tissues, 44 records reported the prognostic value of Ki-67/MKI67 in GC, and 26 records assessed the relationships between Ki-67/MKI67 and clinicopathological parameters." (PMID 31632479, 2019). "The pooled HRs from a random-effects model indicated that an elevated expression of Ki-67/MKI67 predicted a poor OS (HR: 1.54, 95% CI: 1.33-1.78, P<0.0001; I2=69.6, P<0.0001) and DFS (HR: 2.28, 95% CI: 1.43-3.64, P<0.0001; I2=65, P=0.014) in patients with gastric cancer." (PMID 31632479, 2019).
metastatic disease (153 papers, 1991 to 2025). "There is a growing body of evidence describing tumor biomarker conversion, i.e. upregulation or downregulation of hormone receptors, HER2/ERBB2 and Ki-67/MKI67 when comparing metastatic tumors (MT) with primary tumors (PT)." (PMID 28881657, 2017).
ovarian carcinoma (131 papers, 2000 to 2025). A malignant neoplasm originating from the surface ovarian epithelium. "Thereafter, we examined the association of MKI67 level with patient survival from 4 large-scale cancer datasets (including BC, LC, liver cancer and ovarian cancer) based on Kaplan–Meier Plotter." (PMID 34724892, 2021). "MKI67 (Ki-67) is a well-known proliferation marker associating with prognosis and has been used as a target in an ovarian cancer model system." (PMID 26735499, 2016).
hepatocellular carcinoma (128 papers, 1999 to 2026). A malignant tumor that arises from hepatocytes. "An experiment on MKI67 indicated that the cellular growth of hepatocellular carcinoma can be suppressed by targeting MKI67 through miR-519d." (PMID 28587194, 2017). "For example, IGF2BP1 is involved in liver carcinogenesis by binding to and stabilizing the c-MYC and MKI67 mRNAs, and it is an important pro-tumorigenic factor for hepatocellular carcinoma." (PMID 27588393, 2016). "Notably, one transcript, the proliferation marker Ki-67 (MKI67), is stabilized by IGF2BP1 in hepatocellular carcinoma." (PMID 32761127, 2020). "In hepatocellular carcinoma, IGF2BP1 can bind and stabilize c-MYC and MKI67 mRNAs, increase the expression of c-MYC and MKI-67 proteins, which are effective regulators of cell proliferation and apoptosis, and thus participate in regulation of tumor progression." (PMID 33552994, 2020).
pancreatic cancer (125 papers, 2009 to 2025). "Common markers, such as Acta2, Mki67 and Krt19, were expressed in specific subpopulations, confirming the pancreatic cancer cell identity." (PMID 40621620, 2025). "Further analysis using the public database GEPIA revealed that the expression of six genes (PLK1, SPC24, KIF2C, TOP2A, MKI67, and KIF4A) was significantly associated with overall survival in pancreatic cancer patients." (PMID 38250721, 2024). "Among these, PLK1, SPC24, KIF2C, TOP2A, MKI67, and KIF4A, have been implicated in cancer development and serve as important biomarkers of proliferative activity in pancreatic cancer." (PMID 38250721, 2024). "The CTC-pro cluster was most similar to both the NB508 pancreatic cancer cell line and MEFs, and it was enriched for the cellular proliferation marker Mki67 when compared to CTC-c." (PMID 25242334, 2014).
bladder cancer (117 papers, 1991 to 2026). "Furthermore, scRNA-seq data revealed high SKA3 and MKI67 expression in specific epithelial cell subpopulations of bladder cancer tissue." (PMID 34572901, 2021). "The impact on MIBC and NMIBC as prognostic biomarker superior to clinicopathologic parameters and MKI67, raises FOXM1 to a crucial biomarker for molecular grading and to valuable drug target in bladder cancer." (PMID 29959570, 2018).
lung adenocarcinoma (92 papers, 2006 to 2026). A carcinoma that arises from the lung and is characterized by the presence of malignant glandular epithelial cells. "To this end, we analyzed the correlation between CKS2 and MKI67 and PCNA, which were involved in the proliferation of lung adenocarcinoma cells, and found that CKS2 was significantly positively correlated with both of the genes." (PMID 36010686, 2022). "LINC01667 can act as a sponge to regulate genes such as CCNB1, CEP55, MKI67, and TYMS, and ultimately affect the progression of lung adenocarcinoma." (PMID 34458133, 2021). "The intersections of LPS induction-related genes, lung adenocarcinoma differential genes, and univariate cox genes were obtained, and five genes (TNS4, PRC1, MKI67, CDKN3, BIRC5) were obtained, which were defined as the characteristic genes associated with LPS induction." (PMID 40697537, 2025). "MKI67, PCNA, and AURKA are largely prognostic in the same cohorts with renal papillary cell carcinoma, lower-grade brain glioma, renal clear cell carcinoma, pancreatic adenocarcinoma, and lung adenocarcinoma." (PMID 32913979, 2017).
psoriasis (79 papers, 2009 to 2026). An autoimmune condition characterized by red, well-delineated plaques with silvery scales that are usually on the extensor surfaces and scalp. "Machine learning pinpointed MPHOSPH6, ENO1, MKI67, and FABP5 as lactylation-related biomarkers for psoriasis, with ROC curves confirming their strong diagnostic capabilities." (PMID 41909697, 2026). "Cell cycle transcripts, which are elevated in both psoriasis and atopic dermatitis Trm2 compared to healthy controls, also show higher than median dispersion scores, including MKI67 (0.358), TOP2A (0.276), and CENPF (0.356)." (PMID 35958578, 2022). "A shift in the balance betweenthe metalloproteinases in the skin coincides with an aggravation of psoriasis.In turn, an increase in the mki67 level is indicative ofhyperproliferation of keratinocytes.An elevated mki67 expression is animportant characteristic of lesional psoriatic skin." (PMID 24455190, 2013). "In addition, 8 genes (DEFB103A, OASL, HERC6, ISG15, MKI67, MX1, MXD1, SCO2) were considered to have statistically significant differences in sensitivity of short-term treatment for psoriasis." (PMID 40560938, 2025).